NLRP7 (NLR family pyrin domain containing 7)
Diseases named in the same sentence as NLRP7 in open-access papers (continued):
Sharing a sentence is not in itself a finding about the gene and the disease.
mole (2 papers, 2023 to 2025). "Molecular genotyping can be helpful in differentiating between androgenetic and biparental complete mole, and also in identifying germline mutations in NLRP7 and KHDC3L genes, responsible for recurrent mole." (PMID 40361748, 2025). "The gestational history in conjunction with the diagnosis of the type of mole can direct the management towards testing for mutations in NLRP7 or KHDC3L genes." (PMID 38137915, 2023).
ovarian carcinoma (2 papers, 2021 to 2024). A malignant neoplasm originating from the surface ovarian epithelium. "In ovarian cancer, NLRP7 influences cancer cell survival by regulating apoptosis and autophagy, with low expression linked to tumor progression and invasiveness." (PMID 39697539, 2024). "NLRP7 is differentially expressed in 14 tumors and is also induced in ovarian cancer and testicular germ cell cancers in particular, like in our RNA profiling datasets." (PMID 33426787, 2021). "NLRP7 also appears to regulate the stress response and drug resistance in ovarian cancer cells." (PMID 39697539, 2024).
placental diseases (2 papers, 2020 to 2021). "Accumulated evidence indicates that these mutations and nonsynonymous variants (NSVs) of NLRP7 are highly related to a spectrum of gestational placental diseases and spontaneous abortion." (PMID 34068021, 2021). "Here, we established iPSCs-derived trophoblasts from an HM patient with impaired NLRP7 expression and showed that these cells provide a model to investigate human placental diseases." (PMID 32814763, 2020). "Our human iPSC model of a genetic placental disease recapitulates aspects of trophoblast biology, highlights the broad utility of iPSC-derived trophoblasts for modeling human placental diseases and identifies NLRP7 as an essential modulator of key developmental cell fate regulators." (PMID 32814763, 2020).
benign tumor of the placenta (1 paper, 2021). "NLRP7 is the major gene responsible for recurrent CHM, a benign tumor of the placenta that may develop into CC in 5–20% of cases." (PMID 34203890, 2021).
female reproductive cancer (1 paper, 2021). "The clinical relevance of NLRP7 in this rare female reproductive cancer highlights its therapeutic promise as a molecular target." (PMID 34203890, 2021).
hepatic mesenchymal hamartoma (1 paper, 2021). "Many hepatic mesenchymal hamartoma (HMH) cases are associated with cytogenetic alterations at 19q13.4, a genomic region containing NLRP2 and NLRP7." (PMID 34068021, 2021).
lung carcinoma (1 paper, 2024). "Immunofluorescence revealed enhanced apoptosis and inflammation in lung cancer cells, especially in NLRP7 knockdown cells treated with AH-6809." (PMID 39697539, 2024).
pancreatic cancer (1 paper, 2024). "Low expression of NLRP7 has been linked to enhanced anti-apoptotic abilities in pancreatic cancer, making it a potential therapeutic target." (PMID 39697539, 2024).
placental tumors (1 paper, 2021). "Similar to the results obtained on placental tumors, less proliferating and hCG-secreting cells were observed in JEG3-Sh-NLRP7 tumors." (PMID 34203890, 2021). "To determine whether the tumor environment contributes to tumor growth, we compared the mouse transcriptome around placental tumors of eight mice injected with JEG3-Sh-CTL and seven mice injected with JEG3-Sh-NLRP7 using RNA-seq analysis." (PMID 34203890, 2021).
pregnancy disease (1 paper, 2015). "However, a clear effect of harvesting ZBTB16 to the cytoplasm when the NLRP7 protein is overexpressed may be linked to the pathology of the molar pregnancy disease." (PMID 26121690, 2015).
staphylococcus aureus infection (1 paper, 2022). An infectious process in which the bacteria Staphylococcus aureus is present. "Activation of this proposed inflammasome following Staphylococcus aureus infection has been suggested to require ATP binding at the NLRP7 Walker A motif, as well as being regulated by NLRP7 ubiquitination." (PMID 35832835, 2022).
testicular cancer (1 paper, 2021). A primary or metastatic malignant neoplasm that affects the testis. "In testicular cancer, NLRP7 has been shown to play a role in cell proliferation." (PMID 34203890, 2021).
uterine carcinoma (1 paper, 2014). A carcinoma involving a uterus. "For uterine carcinoma, the somatic mutations on two genes were significantly enriched in protein pocket regions: DOK2 (P = 1.1 × 10-4) and NLRP7 (P = 3.2 × 10-4)." (PMID 25360158, 2014).
vitiligo (1 paper, 2025). Generalized well circumscribed patches of leukoderma that are generally distributed over symmetric body locations and is due to autoimmune destruction of melanocytes. "Finally, we obtained ten matched genes (GP1BA, ANKS4B, CCDC87, CA8, HLA‐DOB, RHEBL1, NLRP7, GZMH, HERPUD1, and MAP2K1) as a vitiligo‐gene signature (VGS)." (PMID 40974370, 2025).
tumor (34 papers, 2008 to 2024). "For instance, NLRP7 was particularly associated with immune response pathways, indicating its involvement in modulating the tumor immune microenvironment." (PMID 39697539, 2024). "NLRP7 deubiquitination by USP10 promotes tumor progression and tumor-associated macrophage polarization in CRC." (PMID 36874086, 2023). "USP10 has been reported to deubiquitylate NLRP7 at Lys379 to enhance its stability and expression to promote tumor progression and tumor associated M2 macrophage polarization in colorectal cancer." (PMID 35800898, 2022). "In this study, we showed that NLRP7 is upregulated at the protein level in CRC samples compared with matched non-tumor controls, and that overexpression of NLRP7 is associated with poor prognosis of CRC patients." (PMID 33838681, 2021). "More importantly, this study demonstrated that NLRP7 knockdown in CC tumor cells was associated with a decrease in the expression of numerous proteins involved in maternal immune tolerance such as HLA-G, PDL1, and hCG." (PMID 34203890, 2021). "At the level of genetic mutations, about 111 of 399 (approximately 27.82%) tumor samples represented mutations of pyroptosis-related genes, and NLRP7 accounted for the most." (PMID 34966747, 2021). "AH-6809 likely reverses the molecular characteristics induced by NLRP7 dysregulation, promoting tumor-suppressive effects." (PMID 39697539, 2024). "Literature analysis further supported AH-6809’s tumor-suppressive activity, particularly in NLRP7 knockdown cells, where it inhibited cell growth and facilitated apoptosis." (PMID 39697539, 2024). "Recently, we have demonstrated that NLRP7 is highly expressed in GC tumor cells and contributes to their tumorigenesis." (PMID 36980199, 2023). "Histological comparison of the lungs collected from mice injected with JEG-3 Sh CTL or JEG-3 Sh NLRP7 showed that tumor development was observed in 71% of lungs collected from the JEG-3 Sh CTL group versus only 14% of lungs from the JEG-3 Sh NLRP7 group." (PMID 36980199, 2023). "In tumor trophoblast cells, NLRP7 is overexpressed and functions in an inflammasome-independent manner." (PMID 36980199, 2023). "Here, we further confirmed, at the cellular level, that NLRP7 knockdown leads to a decrease in the expression of key genes known to confer camouflage to tumor cells from their environment." (PMID 36980199, 2023). "NLRP7 involvement in tumor cell growth and tolerance was further characterized in vivo using the metastatic mouse model of GC." (PMID 36980199, 2023). "In non-tumor trophoblast cells, NLRP7 is expressed at normal levels and functions in an inflammasome-dependent manner." (PMID 36980199, 2023). "The proposed review will summarize recent advances in the understanding of NLRP7 involvement in normal and tumor placenta development." (PMID 35203462, 2022). "The absence of mature IL-1β in malignant cells strongly suggests that NLRP7 functions in an inflammasome-independent pathway, which contributes to the exacerbation of tumor-dependent cell proliferation and invasion." (PMID 35203462, 2022). "We have also demonstrated that NLRP7 increases trophoblast proliferation and decreases their differentiation, both in normal and tumor conditions." (PMID 35203462, 2022). "The staining of NLRP7 was heterogeneous in advanced tumors and NLRP7 was frequently located at the invasion front of the tumor." (PMID 35203462, 2022). "In animal studies, macrophages were reduced in the TME of xenograft tumor tissues in NLRP7 and USP10 knockdown groups and were increased in the NLRP7 overexpressing group." (PMID 33838681, 2021). "We showed that NLRP7 promotes CRC progression and revealed an as-yet-unidentified mechanism by which NLRP7 induces the polarization of pro-tumor M2-like macrophages." (PMID 33838681, 2021). "Collectively, these results indicated that upregulated NLRP7 protein in CRC promotes tumor cell proliferation and metastasis." (PMID 33838681, 2021).
tumor (continued). "The expression levels of CCL2 in peripheral blood and tumor tissues were significantly lower in sh-NLRP7-treated and sh-USP10-treated mice than in control mice and higher in NLRP7-treated mice with USP10 knockdown." (PMID 33838681, 2021). "NLRP7 promoted tumor cell proliferation and metastasis in vivo and in vitro and interacted with ubiquitin-specific protease 10, which catalyzed its deubiquitination in CRC cells." (PMID 33838681, 2021). "It was particularly relevant to determine the effect of NLRP7 knockdown on tumor formation by JEG3 cells in 3D culture systems, which form structures and topologies similar to the ones observed in vivo." (PMID 34203890, 2021). "Tumor xenograft experiments showed that NLRP7 or USP10 knockdown inhibited the growth of HCT116 tumors in vivo, whereas overexpression of NLRP7 in USP10 knockdown cells had a synergistic effect on tumor growth." (PMID 33838681, 2021). "The study demonstrates that NLRP7 is directly involved in CC growth and downregulates the maternal immune response, thus fostering tumor growth and dissemination." (PMID 34203890, 2021). "In tumor cells, NLRP7 functions in an inflammasome-independent manner and promoted their proliferation and 3D organization." (PMID 34203890, 2021). "Densitometry analysis showed that five cytokines, IL-4, AXL, IL-1β, IL-9, Exotaxine-2 and IL2, were upregulated, and two cytokines, PF4 and IL-6, were downregulated in the tumor environment of JEG3-Sh-NLRP7 cells." (PMID 34203890, 2021). "Functional studies in vitro and in vivo revealed that NLRP7 promoted tumor cell proliferation and metastasis." (PMID 33838681, 2021). "The present work demonstrates the direct involvement of NLRP7 in the development of CC and provides the evidence of its contribution to the development of an immunosuppressive microenvironment that fosters tumor growth and progression." (PMID 34203890, 2021). "Using both the colony and spheroid formation techniques, we demonstrated that NLRP7 knockdown decreased the initial processes of tumor formation." (PMID 34203890, 2021). "Collectively, the in vitro and in vivo results suggest that NLRP7 is involved in the effect of USP10 on promoting tumor progression and metastasis in CRC." (PMID 33838681, 2021). "The link between overexpression of NLRP7 and tumor development suggests that NLRP7 participates in cell proliferation and/ or cell differentiation." (PMID 18648497, 2008). "Further gene silencing experiments revealed that treatment with AH-6809 significantly inhibited cell proliferation and induced apoptosis, an effect reversed in NLRP7 knockout cells, indicating that NLRP7 plays a crucial role in regulating tumor cell proliferation and apoptosis." (PMID 39697539, 2024). "Collectively, NLRP7 is a key regulator of tumor cell survival and migration, and targeting its expression or activity could represent a novel therapeutic strategy against LUAD brain metastasis." (PMID 39697539, 2024). "Activating NLRP7 may restore immune balance in the tumor microenvironment, thereby inhibiting metastasis." (PMID 39697539, 2024). "In addition, HTR8/SVneo cells overexpressing NLRP7 were used to determine the impact of NLRP7 overexpression on non-tumor cells." (PMID 36980199, 2023). "The present study also brought evidence of NLRP7 involvement in the differentiation of tumor cells through the induction of embryonic markers such as NANOG, NOTCH1 and OCT3/4, and the activation of their survival through the induction of genes, such as CD74 and its co-receptor CXCR2." (PMID 36980199, 2023). "Altogether, these findings strongly suggest that NLRP7, through these functions, may contribute to the evasion of tumor cells from the maternal immune system and their camouflage, which in turn may contribute to their growth and invasiveness." (PMID 36980199, 2023). "We and others have demonstrated that NLRP7 is involved in non-tumor cell differentiation." (PMID 36980199, 2023).
tumor (continued). "This study demonstrated that NLRP7 was upregulated in tumor cells, and in CHM and CC placentae." (PMID 35203462, 2022). "Furthermore, we show that NLRP7 plays another important role in tumor development, through its influence on tumor cells environment." (PMID 34203890, 2021). "In addition, NLRP7 promoted the polarization of pro-tumor M2-like macrophages in CRC by inducing the secretion of C-C motif chemokine ligand 2 (CCL2) through the activation of the NF-κB signaling pathway." (PMID 33838681, 2021). "Moreover, macrophages (F4/80) were reduced in the tumor microenvironment (TME) of xenograft tumor tissues in NLRP7 knockdown group compared with control, as detected by immunohistostaining." (PMID 33838681, 2021). "NLRP7 and circulating inflammatory cytokines were upregulated in tumor cells and in CHM and CC." (PMID 34203890, 2021). "We then proposed the hypothesis that a high level of NLRP7 in CRC may promote tumor progression, requiring further investigation." (PMID 33838681, 2021). "The function of NLRP7 in promoting tumor cell proliferation and metastasis was confirmed." (PMID 33838681, 2021). "On one hand, the pivotal role of NLRP7 in inflammation and cancer immunity, as well as association with tumor metastasis is revealed; on the other, L1CAM was reported to get involved in tumor invasiveness across a number of malignancies except for LUAD metastases which remains controversial." (PMID 39697539, 2024). "This suggested that NLRP1 and NLRP7 may be involved in tumour progression in LUAD." (PMID 34226539, 2021). "Therefore, upregulation of NLRP7 in CRC facilitated tumor cell proliferation and metastasis." (PMID 33838681, 2021). "We proposed the hypothesis that a high level of NLRP7 in CRC may promote tumor progression." (PMID 33838681, 2021). "Here, we investigated the mechanism by which NLRP7 controls these processes in malignant (JEG-3) and non-tumor (HTR8/SVneo) trophoblastic cells." (PMID 36980199, 2023). "We previously demonstrated that NLRP7 is highly expressed in the human GC cell line, JEG-3, compared to the normal (non-tumor) trophoblast cell line, HTR8/SVneo." (PMID 36980199, 2023). "Three genes (ELANE, NLRP7, and CASP5) were downregulated, whereas seven others (GSDMC, IL1A, NOD2, GZMB, GSDMA, IL1B, and PLCG1) were overrepresented in the tumour group." (PMID 35087586, 2022). "Using this model, we compared tumor formation and growth by injecting JEG3-Sh-CTL or JEG3-Sh-NLRP7 in the placenta of gravid mice." (PMID 34203890, 2021). "NLRP7 protein levels were increased by USP10-mediated deubiquitination in CRC cells, which induced the polarization of pro-tumor M2-like macrophages via NF-κB pathway-mediated CCL2 secretion." (PMID 33838681, 2021). "First, we demonstrated that NLRP7 overexpression in GC cells drove its function in an inflammasome-independent manner, which conferred to this member of the NOD-like family a new mechanism of action in GC tumor cells." (PMID 36980199, 2023). "Moreover, NLR family pyrin domain containing 7 (NLRP7), a member of the nucleotide-binding oligomerization domain (NOD) -like receptor family, promotes proliferation and metastasis of tumor cells." (PMID 35884607, 2022). "NLRP7 stability and protein levels in CRC cells were modulated by ubiquitination and deubiquitination, and NLRP7 was involved in the ubiquitin-specific protease 10 promotion of tumor progression and metastasis in CRC." (PMID 33838681, 2021). "Because high levels of CCL2 are correlated with increased numbers of TAMs in tumor tissues in many human tumors, we speculated that the recruitment of TAMs by CCL2 is involved in the function of NLRP7 in promoting CRC progression." (PMID 33838681, 2021). "We found that 25 out of the 33 tested inflammasome-related genes were detectable by quantitative RT-PCR, and 8 of them (CIITA, NLRC4, NLRP3, NLRP7, AIM2, RIG-I, ASC and IL-1β) were overexpressed (fold change, >2) in NPC tumour samples, compared to adjacent normal samples." (PMID 23065753, 2012).
tumor (continued). "Altogether, these results demonstrate that NLRP7-mediated NF-κB activation is mainly operating in non-tumor cells, which may be related to the lack of expression of NLRP7 inflammasome effectors in JEG-3 cells." (PMID 36980199, 2023). "Since aerobic glycolysis contributes to tumor cells’ aggressiveness and is characterized by a massive increase in glucose consumption and lactate production, we compared lactate concentration in the conditioned media of JEG-3 Sh CTL and JEG-3 Sh NLRP7 cells at different time points." (PMID 36980199, 2023). "Importantly, NLRP7 is not the unique member of the NOD-like family that may function in an inflammasome-independent manner in tumor settings." (PMID 36980199, 2023). "Again, tumor cells in the JEG3-Sh-NLRP7 condition expressed less HLA-G and PD-L1, and mouse macrophages appeared to slightly infiltrate the JEG3-Sh-NLRP7 tumors but not the JEG3-Sh-CTL tumors." (PMID 34203890, 2021). "The CM from NLRP7 overexpressing CRC cells, but not the control medium, upregulated the mRNA expression of VEGF and ARG1 which were used as indicators for the functional polarization of TAMs promoted by tumor signals." (PMID 33838681, 2021).